CDK4 (cyclin dependent kinase 4)
Diseases named in the same sentence as CDK4 in open-access papers (continued):
Sharing a sentence is not in itself a finding about the gene and the disease.
bladder cancer (51 papers, 2005 to 2025). "We analyzed the response to the CDK4/6 inhibitor palbociclib in bladder cancer cells over a 48-hour time course using RNA sequencing and identified a multi-step mechanism of response." (PMID 39461947, 2024). "To this end, we performed a transcriptome analysis in bladder cancer cells treated with the CDK4/6 inhibitor PD at six time points from 0–48h after treatment." (PMID 39461947, 2024). "Here we show that in combination CDK4/6 inhibitors potentiate the anti-tumor effect of the oncolytic adenovirus XVir-N-31 in bladder cancer and murine Ewing sarcoma xenograft models." (PMID 35948546, 2022). "Research has shown that CDK4/6 inhibitors are active as a novel therapeutic approach in vitro and in vivo in bladder cancer cells." (PMID 35463324, 2022). "The effects of different CDK4/6 inhibitors were tested on bladder carcinoma cell lines with different CDK6 expression levels." (PMID 35463324, 2022). "Consistently, western blot analysis revealed that gemcitabine and MK-8776 treatment for 48 h suppressed the expression of CDK4 and cyclin D1 in bladder cancer cells." (PMID 33986399, 2021). "Patients with bladder cancer present urothelial cell cycle dysregulation including aberrant activity of CDK4, while overexpression of HGF is known to be involved in early stages of carcinogenesis." (PMID 34232958, 2021). "Palbociclib, the CDK4/6 inhibitor, can promote apoptosis of bladder cancer cells by inhibition of DNA repair following radiotherapy." (PMID 34484337, 2021). "Previously, our group identified molecular factors conferring resistance to CDK4/6 inhibition in bladder cancer (BLCA) that also included components within the DNA repair pathway." (PMID 33923231, 2021). "Recently, our group demonstrated that the JAK-STAT pathway plays a role in acquired resistance of CDK4/6 inhibitors in bladder cancer." (PMID 32046095, 2020). "In conclusion, we show that targeting of STAT3 along with chemotherapy or CDK4/6 inhibitors provide potential combination therapy options in order to improve therapy efficacy in bladder cancer." (PMID 32046095, 2020). "Targeted therapies against CDK4/6 pathway in bladder cancer showed promising data in various preclinical studies." (PMID 32046095, 2020). "Previously, our group applied a genome wide CRISPR-dCas9 screen to identify acquired resistance mechanisms to the CDK4/6 inhibitor Palbocicib in bladder cancer cell lines." (PMID 32046095, 2020). "A genome-scale CRISPR-dCas9 activation screen for resistance to the CDK4/6 inhibitor Palbociclib was performed in the bladder cancer derived cell line T24." (PMID 31331377, 2019). "MiR-1180 is reported as a tumor suppressive miRNA in bladder cancer cells and inhibits cell proliferation and tumorigenicity by inhibiting cell cycle related proteins including CDK4, CDK6, cyclinD1, cyclinA2 expression and up-regulating p21 expression." (PMID 30936781, 2019). "Two additional genes, CCND1 and RB1, identified in the bladder cancer signaling network are known biomarkers, and the third gene identified in the bladder cancer signaling network (CDK4) is a known inhibitor of bladder cancer." (PMID 29912931, 2018). "In urinary bladder cancer, the chromosomal region housing CDK4 was found amplified, and chromosomal amplification has been documented to correlate with reduced survival and to be consistent with increased tumour grade, and genetic instability." (PMID 16265353, 2005). "Similarly, combination of cisplatin and CDK4/6 inhibitors has significantly reduced bladder cancer growth." (PMID 36266723, 2022). "For example, research using the CRISPR-dCas9 screening approach in bladder cancer has indicated the beneficial effects of a combination of CDK4/6 inhibitors with some inhibitors against PI3K-Akt, Ras/MAPK, JAK/STAT, or Wnt signaling pathways in bladder cancer therapy." (PMID 35463324, 2022).
bladder cancer (continued). "p27KIP1 level associated with CDK2 and CDK4 also increased in both MSSV-treated bladder cancer cells as opposed to the untreated cells." (PMID 33430488, 2021). "Additionally, p21WAF1 level in CDK2 and CDK4 complexes in MSSV-treated bladder cancer cells was higher than that in the untreated cells." (PMID 33430488, 2021). "Similarly, another study also reported decreased expression levels of cyclin D1, cyclin E, CDK2 and CDK4 in bladder cancer cells in a dose-dependent manner (0, 25, 50, 100 μg/mL) after 24 h of fucoidan treatment (undefined species source)." (PMID 32046368, 2020). "Potential biomarkers such as CDK4 andSTAT3 may be targets for molecular based therapeutic strategies in the prevention or management of bladder cancer." (PMID 32102537, 2020). "Inhibiting cancer cell proliferation via targeting Cdk4/6 and other cell cycle regulators is a therapeutic strategy which appears to show much promise in the treatment of several solid tumor types, including bladder cancers." (PMID 30875757, 2019). "We applied a combination of a forward genetic screen using CRISPR-dCas9 technology and the analysis of large-scale cancer genomics data sets from patients to identify molecules and signaling pathways that confer resistance to the CDK4/6 inhibitor Palbociclib in bladder cancer." (PMID 31331377, 2019). "It is noteworthy that the deletion of CDKN2A and CDKN2B, key regulators of Cdk4/6 expression, occurs in ~50% of bladder cancers, as this indicates that many MI-BC patients may be responsive to Cdk4/6 inhibitors." (PMID 30875757, 2019). "Therefore most malignancies should be susceptible to CDK4/6 inhibition, and preclinical studies reported that CDK4/6 inhibition of RB positive bladder cancer cells was effective in limiting cell proliferation." (PMID 30349650, 2018). "Our previous study showed that overexpression of miR-195 could induce G1-phase arrest by targeting the novel target CDK4 in bladder cancer cells." (PMID 26337460, 2015). "One recent study demonstrated that metformin could arrest bladder cancer cells in the G0/G1 phase with concomitant decreases in the expression of cyclin D1, CDK4 and E2F1, which is verified again in our study." (PMID 26245871, 2015). "miR-195, as a tumor suppressor in bladder cancer cells, could induce G1-phase arrest by targeting the novel target CDK4." (PMID 26337460, 2015). "CCND1 amplified bladder cancers may be sensitive to CDK4 inhibitors; ERBB2 amplified tumors may be sensitive to lapatinib, trastuzumab, or T-DM1; and MDM2 inhibitors are in current clinical development." (PMID 23593348, 2013). "CDK6 is showed to be overexpressed in bladder cancer, and the concept has emerged that Rb phosphorylation by CDK4/6 leads not only to critical E2F-dependent transcription of essential cell cycle enzymes and regulators but also to assembly of the pre-replication complex in G1 phase." (PMID 24069260, 2013). "Our results also demonstrated that metformin could arrest bladder cancer cells in the G0/G1 phases with concomitant decreases in the expression of cyclin D1, CDK4 and E2F1." (PMID 24351837, 2013). "Then, we performed WB experiments on bladder cancer cell lines with knockdown or overexpression of IGF2BP3 to investigate the expression changes of multiple cyclin proteins CDK2, CDK4, CDK6, and CCND1." (PMID 40083693, 2025). "The results showed that compared with normal tissues, ESR1, PTGS2 and BCL2 in bladder cancer tissues were significantly down-regulated; CASP3, INS, SRC, CDK4, GSK3B and ERBB2 were significantly up-regulated." (PMID 41287122, 2025). "CDK4, KPNA2, PFDN5, HSP90B1, and ZNF121 were identified as prognostic differential genes in bladder cancer." (PMID 37433010, 2023).
bladder cancer (continued). "The present study was aimed to explore the expression of CDk4 and STAT3 in bladder cancer tissues as prospective for target therapy." (PMID 32102537, 2020). "Some of these genes were closely related to the occurrence and development of bladder cancer: CDK6, IL-10, and RUNX1, of which CDK4/6 inhibitors are a promising treatment strategy for the treatment of bladder cancer." (PMID 32655621, 2020). "Finally, our findings provided compelling evidence that the combined administration of CDK4/6-targeting inhibitors palbociclib and cisplatin effectively counteracted the oncogenic effects of IGF2BP3 and overcomes chemotherapy resistance in bladder cancer." (PMID 40083693, 2025). "Morin decreases CDK2, CDK4, cyclin D1, and cyclin E via modulation of the p21/WAF1 pathway, suppressing c-Jun N-terminal kinase (JNK) and AKT phosphorylation, and preventing MMP-9 expression by repressing NF-κB, SP-1, and AP-1 in EJ bladder cancer cells." (PMID 33996570, 2021). "The present study was aimed to explore the expression of CDk4 and STAT3 in bladder cancer tissues." (PMID 32102537, 2020). "Our results showed a good correlation of the expression patterns of both the cell cycle (CDK4) and inflammatory (STAT3) markers studied and might be helpful for suggesting more selective agents in the therapeutic scenario of bladder cancer in the near future." (PMID 32102537, 2020). "Cycle arrest at G0/G1 transition in human bladder cancer cells may have been due to the enhanced of expression of p21 with a decrease in cyclin E1, CDK2, and CDK4 kinase levels." (PMID 31024833, 2019). "Similarly, CDK4/6 inhibition is a novel therapeutic modality for bladder cancer irrespective of RB1 status." (PMID 36266723, 2022). "In conclusion, Our results showed a good correlation of the expression patterns of both the cell cycle (CDK4) and inflammatory (STAT3) markers studied and might be helpful for suggesting more selective agents in the therapeutic scenario of bladder cancer in the near future." (PMID 32102537, 2020). "Knockdown of GAS5 significantly increases CDK6 mRNA and protein levels in bladder cancer cell lines, but downregulation of GAS5 don’t change CDK2 and CDK4 expression level (data not shown)." (PMID 24069260, 2013). "In addition, analysis of TCGA expression data via gene expression profiling interactive analysis (GEPIA) demonstrated that CDK1, cyclinA2 and cyclinB1 are observed at increased expression levels in bladder cancer tissues, whereas CDK2, CDK4 and cyclinD1 are not differentially expressed." (PMID 40518827, 2025).
cervical carcinoma (45 papers, 2007 to 2025). A carcinoma arising from either the exocervical squamous epithelium or the endocervical glandular epithelium. "Recently, it has been shown that EX-527 and AGK2 decrease Hela cervical cancer cell proliferation associated with G1 phase arrest and the downregulation of CDK4 and/or CDK6." (PMID 29401749, 2018). "Loss of RB1 function, which is a well known phenomenon in cervical cancer leads to expression of Cyclin D1, over-expression/amplification of CDK4, and/or loss of the CDKN1B, CDKN2A and CDKN2B." (PMID 26701206, 2016). "The results showed high P16INK4A expression and its enhanced interaction with CDK4 in cervical carcinoma DDP-resistance cells (SiHa-DPP), which may cause irreversible proliferation arrest." (PMID 25663864, 2015). "Abemaciclib suppresses cervical cancer cell growth and promoted apoptosis via the suppression of CDK4/6-Rb-E2F and mTOR pathways." (PMID 38170401, 2024). "CDK4 is reported to be involved in cervical tumorigenesis, and 72.6% of cervical cancer specimens showed overexpression of CDK4." (PMID 35885925, 2022). "We found inhibitory effects of CAR on cyclin D1 and CDK4 in cervical cancer cells suggesting its interference with cell cycle regulatory proteins." (PMID 36712982, 2022). "CAR efficiently inhibited the growth of cervical cancer cells via arresting the cell cycle at G0/G1 phase and modulated the gene expression of related proteins (p21, p27, cyclin D1 and CDK4)." (PMID 36712982, 2022). "Up‐regulation of CDK4 and Cyclin D1 has been elucidated to be indicative of promoting effects induced by the receptor for activated protein kinase C on cervical cancer cell growth." (PMID 33417281, 2021). "Circ_0000326 also exerts oncogenic effects in cervical cancer by upregulating cyclin-dependent kinase 4 via sponging miR-338-3p." (PMID 34889689, 2021). "All of these results indicated that PRDM4 inhibited cell proliferation and tumor growth, possibly by regulating cell cycle-related genes, including p27, p21, Cyclin D1, and CDK4, in cervical cancer." (PMID 33846573, 2021). "The results of this “proof of concept” study support targeting the cyclin D1/CDK4/6 complex for development of new treatments for cervical cancer." (PMID 32429557, 2020). "Studies had shown that SJAMP inhibited cervical cancer Hela cells proliferation through inhibiting CyclinD1 and CDK4, and induce the differentiation of Hela cells by suppressing the expression of oncogene c-myc." (PMID 28099921, 2017). "The observed inhibitory effects of Cucurbitacin D on cyclin D1, CDK4 and phosphorylation of RB proteins in cervical cancer cells suggests its interference in cell cycle regulatory proteins." (PMID 27824155, 2016). "Cucurbitacin D treatment of cervical cancer cells arrested the cell cycle in G1/S phase, inhibited constitutive expression of E6, Cyclin D1, CDK4, pRb, and Rb and induced the protein levels of p21 and p27." (PMID 27824155, 2016). "Likewise, in cervical cancer, Tspan31 directly silences CDK4 by targeting its 3′-untranslated region (3′-UTR), a master switch controlling cell cycle progression." (PMID 38649381, 2024). "Here, we found that PRDM4 inhibited cell proliferation and tumor formation in cervical cancer by blocking the cell cycle transition from G0/G1 to S phase by regulating cell cycle checkpoint factors, including p21, p27, Cyclin D1, Cyclin E, and CDK4." (PMID 33846573, 2021). "The down‐regulation of CDK4 helps to suppress cell proliferation in human cervical cancer." (PMID 33417281, 2021).
cervical carcinoma (continued). "We hypothesized that cyclin D1 degradation by the SHetA2 drug in combination with palbociclib inhibition of CDK4/6 activity synergistically reduces phosphorylated Rb (phospho-Rb) and inhibits cervical cancer growth." (PMID 32429557, 2020). "Furthermore, consistent with the fact that p21 is a cyclin-dependent kinase inhibitor, we found that levels of cyclin-related proteins such as Cyclin D1, Cyclin E1, CDK2 and CDK4 were reduced in cervical cancer cells overexpressed by ST3Gal IV." (PMID 33598419, 2020). "In addition, western blot further suggested that the expression of CyclinD1 and CDK4 in cervical cancer cells derived CSCs treated with zoledronic acid was decreased in dose-dependent manners." (PMID 30791957, 2019). "In this study, a high level of P16INK4A expression and its enhanced interaction with cyclin-dependent kinase-4 in cervical carcinoma DDP-resistance cells (SiHa-DDP) was identified, which was associated with the inactivation of phosphorylated retinoblastoma protein (pRb)." (PMID 25663864, 2015). "Inhibition of CyclinD1 and CDK4 by curcumin was observed in cervical cancer cells, although it was accompanied by up-regulation of p21, p27 contradicting our data showing down-regulation of p21, and p27 suggesting the complexity of its action involving mediators other than p21 and p27." (PMID 25786122, 2015). "In various cancer cell lines, including those of breast, lung, colorectal, and cervical cancers, PRMT6 has been found to inhibit the expression of cyclin-dependent kinase inhibitors (CKI) such as p21cip1/waf1, p27kip1, and p18ink4c, or to mitigate the association of p16ink4a with CDK4." (PMID 40461482, 2025). "Tspan31 directly silences CDK4, a master switch controlling cell cycle progression, by targeting its 3′-untranslated region (3′-UTR) in cervical cancer, highlighting its ability to modulate cell cycle checkpoints." (PMID 38649381, 2024). "Previous studies have demonstrated that treatment with Astragalus-containing CHM (SH003) reduces the levels of expression for G1 phase-related CDK (CDK2, CDK4, and CDK6) and cyclin D and induces extrinsic cell apoptosis in HeLa cervical cancer cells." (PMID 34393766, 2021). "pointed out that upregulation of SKA3 elevated the expression of CDK4, p-Akt, Cdk2 cyclinE2, p-Rb, E2F1, and cyclinD1 in HeLa cells, thus promoting cervical cancer proliferation and migration." (PMID 34845974, 2021). "Polydatin efficiently inhibited cervical cancer cell proliferation by regulating cell cycle-related proteins including p21, p27, CDK2, CDK4, Cyclin D1, and Cyclin E1." (PMID 33912552, 2021). "The effects of knockdown of ClC-3 expression by ClC-3 siRNA on cell cycle progression and expression of cyclin D1, CDK4, CDK6, p21 and p27 were also tested in the HeLa cell, a cell line derived from cervical cancer cells." (PMID 27451945, 2016). "The USP25/KIFC1/MYCBP signal axis detected by RT-PCR did not change the expression level of c-MYC mRNA, but affected the expression levels of c-MYC transcription targets CDK4, CDK2, cyclin D1 and cyclin E which these have been reported to be regulated by c-MYC transcription in cervical cancer." (PMID 40379626, 2025). "Even though p16 acts as a tumor suppressor in most cellular contexts, as oncoprotein E7 expressed by human papillomavirus (HPV) mediate the degradation of retinoblastoma protein (Rb) 2, a target of the CDK4/6 kinase, the tumor suppressor role of p16 is abolished in HPV transformed cervical cancers." (PMID 32047552, 2020).
cervical carcinoma (continued). "Furthermore, the transcript levels of cell-cycle-promoting factors, such as cyclinD1, cyclinB, CDK4, CDK2, and CDC2, were all inhibited in DAX1-silenced cervical cancer cells." (PMID 29497051, 2018). "In the study of gastric cancer SNU-1 cells and Cervical cancer C33A, SiHA, HeLa cells, Naringin blocked PI3K/AKT pathway and β- Catenin/GSK-3 β Pathways to reduce the expression of cell cycle survival proteins c-Myc, CDK2, CDK4, and Cyclin D1, and increase the expression of p21/cip1 and p27/kip1." (PMID 37663256, 2023). "A previous study demonstrated the cell cycle regulatory mechanism of SHetA2 and its synergistic interaction with cyclin dependent kinase 4/6 inhibitors, however no studies have yet been done on the mechanism of SHetA2-induced cell death of cervical cancer cells." (PMID 36203464, 2022). "In a similar study, seven proteins (AIF-1, ALP2, B-FABP, CDK4, ICA69, NCK- 1, and PRSS1) were upregulated in cancer samples, of which differential expression of B-FABP, CDK4, and NCK-1 was also validated by WB and IHC, and these could be used as potential cervical cancer markers." (PMID 38328436, 2023).